EGFR (epidermal growth factor receptor)
Diseases named in the same sentence as EGFR in open-access papers (continued):
Sharing a sentence is not in itself a finding about the gene and the disease.
breast carcinoma (continued). "Amphiregulin, a ligand of the epidermal growth factor receptor (EGFR), was initially identified as a secreted factor in the ERα-positive MCF7 breast cancer cell line, and was shown to be estrogen-responsive in these cells." (PMID 24010672, 2013). "Analysis of breast cancer and lymph nodes tissue microarrays of the same patients revealed that CXCR4 and CCR7 together with their ligands as well as EGFR were significantly higher expressed in tumor cells with lymph node metastasis." (PMID 23667660, 2013). "ZEGFR:1907, anti-EGFR affibody, modified with different NIR fluorescent dyes have been reported to specifically bind EGFR-positive breast cancer cells." (PMID 23533377, 2013). "The paracrine mediation of oestrogen signalling occurs in the normal breast through the EGFR pathway which activates ERK signalling and we demonstrate that this is also true in breast cancer." (PMID 23497505, 2013). "In our study population of 133 cases of male breast cancer, we found 4 cases (3.0%) expressing HER2, 15 cases (11.4%) EGFR, 6 cases (4.5%) MET, 16 cases (12.1%) FGFR2, and 50 cases (38.5%) IGF1-R." (PMID 23308200, 2013). "In breast cancers, RAS is often activated by HER2 [ErbB2/epidermal growth factor receptor (EGFR) 2/Neu] receptor tyrosine kinase and is over expressed and persistently activated in approximately 25 % of cancers." (PMID 24147022, 2013). "This study aimed to investigate the impact of co-inhibition of EGFR and IGF-1R on the radiosensitivity of two breast cancer cells with different profiles of EGFR and IGF-1R expression." (PMID 23777562, 2013). "Lapatinib (GW572016, Tykerb), a dual EGFR and HER2 tyrosine kinase inhibitor (TKI), has been approved for trastuzumab-resistant HER2-positive advanced breast cancer patients." (PMID 24216290, 2013). "In the normal rat mammary gland and inhormone-dependent rat mammary cancers, AREG has also been shown to mediate E and Psignaling through EGFR." (PMID 23705924, 2013). "It has been shown that the PH domain of GEP100 is associated with phosphorylated Tyr951 of VEGFR2, and its PH domain was also reported to bind to certain phosphorylated tyrosines on EGFR, and mediate EGF-stimulated breast cancer cell invasion." (PMID 22701712, 2012). "Considerable intratumoral heterogeneity was observed for both common and novel protein biomarkers of breast cancer signaling pathways, including HER2, uPA/PAI-1 and EGFR signaling." (PMID 22792263, 2012). "Afatinib has demonstrated preclinical activity in human epidermal growth factor receptor HER2 (ErbB2)-positive and triple-negative xenograft models of breast cancer, and clinical activity in phase I studies." (PMID 22763464, 2012). "Basal-like breast cancers typically express basal cytokeratins such as CK5/6, CK17 as well as cadherin, and epidermal growth factor receptor (EGFR)." (PMID 22295242, 2012). "Two tissue microarray (TMA) slides containing 800 samples of breast cancer tissue immunostained against Ki-67 protein and two TMA slides containing 144 samples of colorectal cancer immunostained against EGFR were digitized with a whole-slide scanner." (PMID 22436596, 2012). "A confrontation of two IHC definitions of basal breast cancers in a series of 3744 cases revealed that the five-biomarker definition (ER, PR, ERBB2, CK5/6 and EGFR) had superior prognostic value than the TN one." (PMID 22082486, 2012). "Increased phosphorylation of EGFR and p38 was already reported as a proapoptotic signal in cancer cells, and especially in the MDA-MB-231 breast cancer cell line." (PMID 22811918, 2012). "HER3, a member of the EGFR/HER family, is frequently overexpressed in breast cancer with EGFR (HER1) or HER2 overexpression." (PMID 22848366, 2012). "We and other have shown that the expression of EGFR is upregulated in Herceptin-resistance and in TNBC subset of breast cancer." (PMID 22957061, 2012).
breast carcinoma (continued). "In contrast to lung cancers that are addicted to EGFR signaling, PI3K inhibition alone can induce apoptosis of HER2-addicted breast cancers." (PMID 23227361, 2012). "In fact, the PH domain of GEP100 was identified to bind directly to Tyr1068/1086-phosphorylated EGFR and was required for EGF-stimulated Arf6 activation in MDA-MB-231 breast cancer cells." (PMID 22701712, 2012). "Numerous studies have also shown that basal-like breast cancer can be specifically identified using IHC surrogate panels including ER, PR and HER2 negativity and either EGFR or CK5/6 positivity (ER-, PR-, HER2-, CK5/6+ and/or EGFR+)." (PMID 23009686, 2012). "In another study, exosomes from breast cancer and colorectal tumors displayed amphiregulin on their surfaces, which engaged with HER1/EGFR on tumor cells to increase their invasiveness." (PMID 22738135, 2012). "In fact, inhibition of HER2 phosphorylation by TKIs targeting EGFR and HER2 in HER2+ breast cancer cells is followed by feedback upregulation of activated ErbB3." (PMID 22889873, 2012). "EGFR was a top hit in MDA-MB-468 cells, a breast cancer cell line that overexpresses EGFR and that is resistant to erlotinib (an EGFR inhibitor); erlotinib previously has been shown to enhance paclitaxel sensitivity." (PMID 23281588, 2012). "RTK mutations have been implicated in a variety of cancers, specifically, members of the epidermal growth factor receptor (EGFR) family in brain, lung, and breast cancer." (PMID 22934183, 2012). "Other genes, like epidermal growth factor receptor (EGFR), Fibroblast growth factor receptor 1 (FGFR1), topoisomerase IIa (TOP2A) and MYC are also involved in female breast cancer and have prognostic and therapeutic implications." (PMID 22527098, 2012). "Our results support that trastuzumab resistance mechanisms are related with deregulation of PTEN/PI3K/Akt/mTOR pathway, and/or EGFR and IGF1R overexpression in a subset of HER2-positive breast carcinomas." (PMID 22454081, 2012). "The results demonstrated that active MMP-1 proteolysed latent TGFα to generate active TGFα, leading to an activated EGFR signal pathway, thus linking MMP-1 and the EGFR signaling pathway in metastatic breast cancer cells." (PMID 23217186, 2012). "Overexpression of EGFR is common in patients with TNBC and is seen in up to 60% of basal-like breast cancers." (PMID 22295242, 2012). "Our results showed that EBP50 can inhibit EGF-stimulated breast cancer cell proliferation and EGFR pathway activation, supporting a role for EBP50 in inhibiting EGF-induced cell proliferation by blocking EGFR phosphorylation in breast cancer cells." (PMID 22476347, 2012). "Lapatinib (Tykerb; GlaxoSmithKline) is a dual EGFR/HER2 kinase inhibitor that reduces EGFR and HER2 signaling and induces apoptosis in multiple models of HER2-overexpressing breast cancer." (PMID 23227361, 2012). "EGFR, HER2, HER3 and membrane bound CXCR4 expression levels of M13SV1-EGFP-Neo breast epithelial cells, MDA-MB-435-Hyg breast cancer cells and M13MDA435-1 hybrid cells were comparable to previously published data." (PMID 22487193, 2012). "Compared to female breast cancers, EGFR (p = 0.005) and CCND1 (p = 0.041) copy number gain was more often seen in male breast cancer, while copy number gain of EMSY (p = 0.004) and CPD (p = 0.001) and amplification in general was less frequent." (PMID 22527098, 2012). "Previously we determined a subline of the aggressive breast cancer cell line MDA-231 efficiently colonizes mouse bone after intracardiac inoculation, expresses high levels of EGFR protein and modest levels of the ErbB2 and ErbB3 receptors, and sheds AREG." (PMID 22276166, 2012). "After the ligation of nAChR with nicotine, EGFR was shown to be activated and then internalized in both MCF10A and MDA-MB-231 breast cancer cells." (PMID 22085699, 2011).
breast carcinoma (continued). "We also found that EGF treatment promoted the internalization of GPR54 in breast cancer cells and that GPR54 and EGFR partially co-localized upon treatment of Kp-10 or EGF." (PMID 21738726, 2011). "In breast cancer cells the interaction between the anti-proliferative GPCRs SSTR1 and SSTR5, and EGFR has been described." (PMID 24212818, 2011). "However, since EGFR expression is associated with decreased survival of breast cancer patients, activating the EGFR through a biased agonist may not be beneficial even if the patient is taking an EGFR inhibitor." (PMID 21476970, 2011). "The observations made in T98G cells were similarly found in cells of the human breast cancer, MDA-MB-468, that express endogenous EGFR, in which the two apoptosis-inducers, staurosporine and anisomycin, were used to stress the cells." (PMID 21388543, 2011). "Thus, Cbp may regulate the synergistic interactions between Src and EGFR in breast cancer." (PMID 21776389, 2011). "For example, we have recently shown that nuclear EGFR interacts with STAT3 and that the interaction contributes to tumor resistance to the anti-EGFR agent, Iressa, in human GBM and breast cancer cells." (PMID 21388543, 2011). "We have shown that EGFR, when activated by its ligand, recruits GEP100 and induces the invasion and metastasis of breast cancer cells." (PMID 21966491, 2011). "The scoring method used here for both EGFR and ERBB2 scoring was chosen because it is extensively and successfully used for ERBB2 in breast cancers in the United Kingdom." (PMID 21364580, 2011). "EGFR induces expression of IRF1, and IRF1 also can regulate EGFR expression, suggesting a possible role of IRF1 in EGFR overexpressing breast cancers." (PMID 22295238, 2011). "EGFR overexpression appears to correlate with the basaloid phenotype and is found in 67% of BRCA1-related cancers versus only 18% of non-BRCA1-related breast cancers." (PMID 21396117, 2011). "Recently, we provided strong evidence that IRS-1 can function as a key signalling intermediate for EGFR, a receptor that drives the growth of a tamoxifen-resistant MCF-7 breast cancer cell line." (PMID 21939528, 2011). "To investigate the molecular changes in HER2 overexpressing breast cancer cells after treatment with the gefitinib and RAD001 combination, we analyzed the expression and phosphorylation of proteins relevant to EGFR, HER2 and mTOR signaling." (PMID 21961653, 2011). "Here, we assessed feasibility of combining the EGFR inhibitor gefitinib and the mTOR inhibitor everolimus (RAD001) for treating HER2 overexpressing breast cancers with different sensitivity to TZ." (PMID 21961653, 2011). "Upon nicotine-induced EGFR activation, Src, Akt and ERK1/2 were phosphorylated in MCF10 and MDA-MB-231 breast cancer cells, leading to the upregulation of E2F-1, Bcl-2 expression, and long-term cell survival." (PMID 22085699, 2011). "Since EGFR and Src signaling pathways contribute to STAT3 activation in breast cancers, we evaluated Necdin expression levels in human breast cancer cell lines with different levels of endogenous STAT3 activity." (PMID 22046235, 2011). "In tamoxifen-resistant breast cancer cells, IGF-1R is upregulated and acts upstream of estrogen-activated EGFR." (PMID 21595894, 2011). "In human breast cancer cell lines, such as MDA-MB-231, the EGFR level is elevated compared with that in other breast cancer cells, such as MCF7; for this reason, we have studied the effects of DHA and EPA on EGFR activity mainly in MDA-MB-231 cells." (PMID 21569413, 2011). "Co-expression of EGFR and HER2 in breast cancer cell lines has been shown to induce drug resistance, including resistance to TZ, and has been correlated with a negative prognosis for breast cancer patients." (PMID 21961653, 2011). "This study investigates the relationship between cPLA2α and EGFR/HER2 in vivo, addressing the clinical implications of differential cPLA2α expression in breast cancer." (PMID 21119660, 2011).
breast carcinoma (continued). "Although a large number of new agents targeting the EGFR pathways are being tested and have shown certain efficacy through greater survival in clinical and pre-clinical models, it remains unclear as to how combination EGFR therapy with chemotherapy will impact breast cancer patients." (PMID 22096483, 2011). "Here, we show that the EGFR inhibitor gefitinib and the mTOR inhibitor RAD001 when used in combination improve effectiveness of the treatment in HER2 overexpressing breast cancers that results in impediment of cancer growth." (PMID 21961653, 2011). "MDA-MB-468, a human breast cancer cell line with a very high number of EGF receptors, shows less EGFR enhanced when trasfected with versican G3 domain." (PMID 22096483, 2011). "High EGFR expression, low ERα, the basal and HER2-positive subtypes are all molecular markers of poor prognosis in breast cancer." (PMID 21119660, 2011). "Results of numerous studies indicate that detection of single mRNA markers like mamoglobin, survivin, HER2, EGFR, VEGF and VEGFR range from 30 to 63% cases in peripheral blood of breast cancers." (PMID 21827674, 2011). "Lapatinib in breast cancer was active predominantly in the presence of phosphorylated EGFR and HER2 while Herceptin is active in breast cancers with increased copy number of HER2 (Fish)." (PMID 22091418, 2011). "We also used IF to evaluate membrane staining of EGFR, pEGFR, HER2 and pHER in CTCs from 20 patients with clinically HER2-positive breast cancer." (PMID 20461092, 2010). "For the first time, we have identified somatic mutations in genes related to the AKT/MAPK signaling pathways, such as EGFR, PIK3CA, KRAS, HRAS and NRAS, in brain metastases of breast cancer and other types of cancer." (PMID 20604919, 2010). "Importantly, EGFR and c-Met were highly expressed in this subset, suggesting that antibodies against these cell surface markers could have utility in capturing this subset of breast cancer cells." (PMID 20838621, 2010). "Using tissue microarray-based immunohistochemical analysis, we categorized 951 primary breast cancers into four or five subtypes according to the expression of ER, PR, HER2, and basal markers (CK5/6, EGFR)." (PMID 20860845, 2010). "The CXCR4, CCR7, CXCL12, CCL21, and EGFR biomarkers were analyzed along with ER, PR, and HER-2/neu in breast cancer tissue microarray (TMA) specimens, including 200 primary breast cancer specimens by immunohistochemistry." (PMID 20181250, 2010). "However, in other cell types, such as mammary epithelial cells, as well as melanoma and breast cancer cell lines, E-cadherin-mediated cell-cell contacts have been shown to suppress proliferation signals that are driven by RTKs, particularly from the EGFR pathway." (PMID 21049033, 2010). "These growth factors activate HER2 and also the other members of the HER receptor family—EGFR, HER3 and HER4—in such a way as to maintain HER2 activation and cell survival in HER2-positive breast cancer cells." (PMID 21203579, 2010). "In human breast cancer cells, AGR2 expression correlates positively with estrogen receptor and negatively with epidermal growth factor receptor expression." (PMID 20525245, 2010). "The EGFR and ERBB3 are overexpressed in 50–70% of lung, colon and breast carcinoma; ERBB2 is overexpressed in 30% of breast cancer patients; ERBB4 is expressed in 50% of breast cancer patients and 22% of colon cancer patients." (PMID 20010942, 2010). "ER, PR, HER2, EGFR and CK5/6 were used as surrogate markers for gene expression profiling to classify 231 breast cancer specimens." (PMID 20492711, 2010). "Lapatinib is a small-molecule tyrosine kinase inhibitor that blocks phosphorylation of the epidermal growth factor receptor and HER2 in breast cancer cells, resulting in apoptosis." (PMID 21080941, 2010). "In the breast cancer study, resistance to gefitinib or erlotinib, agents that act on the EGFR/HER1, was accompanied by increased tyrosine phosphorylation of ErbB3/HER3." (PMID 20670437, 2010).
breast carcinoma (continued). "The epidermal growth factor (EGF) receptor gene (EGFR/HER1/ERBB1) and other EGF receptors (HER2/NEU/ERBB2, HER3 and HER4) are frequently expressed in human breast cancer cells, including MDA-MB-231 cells." (PMID 21029421, 2010). "Lapatinib inhibits EGFR and HER2 phosphorylation in breast cancer cells, and it is an effective treatment for patients with HER2-positive metastatic breast cancer that has progressed after prior therapies." (PMID 21080941, 2010). "Inhibition of the EGFR gene in human breast cancer cells is likely due to recruitment of CBP and SRC-1 from the EGFR promoter by ligand activated PPARs and RXRs." (PMID 21080969, 2010). "HER2 functions as a common co-receptor recruited from EGFR or HER3 upon binding to their ligands and HER2/HER3 heterodimer has been defined as the major oncogenic unit in HER2 positive breast cancer." (PMID 21209853, 2010). "The c-neu gene encodes Erb-B2, a trans-membrane glycoprotein (185 kDa) with tyrosine kinase activity closely related to epidermal growth factor receptor (EGFR), and is overexpressed in twenty to thirty percent of primary human breast cancers." (PMID 19173004, 2009). "To assess the validity of this normalization factor, we applied our model to the quantification of EGFR, HER2 and HER3 expression in LS174T (colon adenocarcinoma) and SKBr3 (breast carcinoma) samples displaying variable RNA integrity." (PMID 19368728, 2009). "Considering ERK1/2 are active in epithelial cancers, including breast cancer, if ERK1/2 requires autocrine activation of EGFR, than the therapeutic blockade of EGFR will block ERK1/2-driven tumorigenic responses." (PMID 19457236, 2009). "In a study of 20 cases of metaplastic carcinomas of the breast, they found that 14/20 MSC's were positive for EGFR expression, highlighting the potential utility of targeted therapies to the EGFR receptor." (PMID 19126225, 2009). "A total of 42 cases of male breast carcinoma were examined retrospectively using immunostains for estrogen receptor (ER), progesterone receptor (PR), cytokeratin 5/6 (CK5/6), EGFR, and NF-κB." (PMID 19442295, 2009). "The most prominent therapeutic monoclonal antibody is Herceptin® (trastuzumab) which is indicated for breast cancers involving the upregulation of HER2, a receptor tyrosine kinase belonging to the epidermal growth factor receptor (EGFR)/HER family." (PMID 19552806, 2009). "Activation and overexpression ofoncogenes encoding trans-membrane receptor tyrosine kinases of the EGFR family,including EGFR (ErbB1) and HER2/neu (ErbB2), play an important role in thedevelopment of breast cancer." (PMID 19424511, 2009). "The activation of the EGFR even by serum-supplemented medium alone therefore significantly altered the motility of MDA-MB-231 and MCF-7 breast cancer cells (P = 0.028 and P = 0.0264 at the end points, respectively)." (PMID 18435854, 2008). "As 31% of TNBCs were positive for EGFR protein in this series, we measured EGFR gene copy number in 63 TNBCs compared with 42 ER and/or PgR-positive but HER2-negative consecutive breast cancers, (which are also termed luminal subtype)." (PMID 18950515, 2008). "The absence of EGFR methylation in the 468GFP cells confirmed a previous report showing that several breast cancer cell lines, including the parental MDA-MB 468 cells, lack DNA methylation at the EGFR promoter." (PMID 18638373, 2008). "More recently Lapatinib which targets the tyrosine kinase activities of both EGFR and HER2 has been shown to be beneficial in HER2 positive patients, confirming the important role of EGFR inhibition in breast cancer." (PMID 18682844, 2008). "Previous studies have examined the value of biomarkers such as carcinoembryonic antigen, CA 15-3, MMP-2, MMP-9, tissue polypeptide antigen (TPA), tissue polypeptide-specific antigen (TPS), EGFR, and HER-2/neu in predicting response to NAC for breast cancer." (PMID 18474099, 2008).